COL4A6 (collagen type IV alpha 6 chain)
Diseases named in the same sentence as COL4A6 in open-access papers (continued):
Sharing a sentence is not in itself a finding about the gene and the disease.
X-linked nonsyndromic hearing loss (1 paper, 2021). X-linked form of nonsyndromic deafness. "Recently, a Hungarian family was reported to have congenital X-linked nonsyndromic hearing loss caused by a mutation in COL4A6 (c.1771G>A, p.Gly591Ser), which was accompanied by cochlear malformation." (PMID 33848312, 2021).
tumor (21 papers, 2009 to 2025). "Among these, COL4A5 and COL4A6 were each statistically co-overexpressed with DDR1 in the 40 tumor tissues." (PMID 32244515, 2020). "COL4A6, a major component of the basement membrane, plays an important role in confinement of the tumor microenvironment." (PMID 25137136, 2014). "COL4A6 may promote tumor aggressiveness and chemoresistance via the E2F/DDR1 axis, and COL4A6 expression can predict clinical outcomes in patients with OC." (PMID 40603853, 2025). "Additionally, studies should explore how COL4A6 interacts with the tumor microenvironment and identify potential therapeutic strategies to modulate its expression or stromal interactions to overcome chemoresistance." (PMID 40603853, 2025). "This study’s principal finding was that COL4A6 played an important role in the regulation of cell aggressiveness, cell proliferation, tumor formation, and chemoresistance and that COL4A6 expression acted as a predictor of poor clinical outcomes in patients with EOC." (PMID 40603853, 2025). "Since the expression of COL4A5 is decreased in GC tumor tissue and a strong positive correlation exists between expression of COL4A5 and COL4A6, the formation and quantity of minor type IV collagens in GC tumor might be affected." (PMID 36596829, 2023). "Downregulation of COL4A6 could change BM constituents, making it possible for invasion or metastasis of tumor cells." (PMID 35711936, 2022). "The mRNA expression level of all six type IV collagen genes (COL4A1, COL4A2 COL4A3, COL4A4, COL4A5 and COL4A6) was higher in metastatic tissue compared to primary tumor tissue, although being significant only for COL4A3 (p = 0.013) and COLA4A4 (p = 0.005) genes." (PMID 35693557, 2022). "Through the data mining of a microarray dataset composed of matched tumor-normal tissues from forty OSCC patients, we distilled overexpressed genes statistically associated with angiolymphatic invasion, including DDR1, COL4A5, COL4A6 and PDPN." (PMID 32244515, 2020). "Similarly, several genes encoding proteins involved in tumor shedding, adhesion and migration, such as collagens (COL4A5, COL4A6), integrins (ITGB4) and laminins (LAMA3), were overexpressed and positively associated with pathogenic bacteria in OSCC tumor microenvironment." (PMID 38589501, 2024). "In terms of the genes that are exclusively affected by tumor-specific somatic TE insertions, we also observed the enrichment of affected genes in the cancer pathway (due to tumor-specific TE insertions in genes such as COL4A6, PLCB4, ARNT2, LRP5, NCOA3, and CTNNA2)." (PMID 35013466, 2022). "We found that the expression levels of seven integrin ligands (COL4A6, COL13A1, FGB, COL19A1, COL18A1, COL14A1, and COL11A2) were negatively correlated with the Gleason score, suggesting that the suppression of integrins and/or their ligands is associated with more advanced tumor grade." (PMID 19653896, 2009). "As the tumor progressed, COL4A1, COL4A2 and COL4A6 expression gradually increased, and COL4A3, COL4A4 and COL4A5 gradually decreased." (PMID 40351420, 2025). "Correlation among the 9 down-regulated collagen genes in GC tumor was also analyzed, and the results showed that a strong positive correlation existed between the mRNA expression of COL4A5 and COL4A6." (PMID 36596829, 2023). "In our NCKU-OrCA-40TN cohort, we noticed that five collagen subunits are upregulated genes in the tumor tissues compared to that in the normal counterparts, including COL1A1 (3.5×), COL4A1 (2.1×), COL4A2 (3.3×), COL4A5 (5.6×), and COL4A6 (9.2×)." (PMID 32244515, 2020). "Differential expression analysis using GSEA and Limma of the 40 tumor transcriptomes consistently revealed DDR1, PDPN, and COL4A6 as top upregulated genes in tissues with ALI compared to those without (Table A1, Figure A1)." (PMID 32244515, 2020). "Similarly, COL4A6 was positively correlated with macrophage, neutrophil and CD4 + T cell immune infiltration, however, negatively correlated with tumor purity." (PMID 38907304, 2024).
tumor (continued). "Therefore, our study found that during PCa pathogenesis, the disorganized expression of CRISP3, OGN, SPOCK3, COL4A6, CCBE1, and FLRT3 leads to ECM dysfunction and promotes angiogenesis and tumor development." (PMID 37251946, 2023). "COL4A6 (collagen type IV alpha 6 chain) is a member of the COL4A family, a major component of the basement membrane (BM), which may be involved in tumor angiogenesis and progression." (PMID 35711936, 2022). "Examples are COL4A6, WNK2 and STK32B whose roles have been assigned in processes such as prevention of early invasion stages, negative regulation of epidermal growth factor receptor signaling and opposite correlation with tumor size, respectively." (PMID 33691672, 2021). "However, the expression level of COL4A6 slightly increased with TNM stage, which may imply its different roles in the tumor environment and needs to be further explored." (PMID 35711936, 2022). "Experimental design: Eight novel candidate markers, COL4A6, CYBA, TCAF1 (FAM115A), HLF, LINC01341 (LOC149134), LRRC4, PROM1, and RHCG, were selected from Illumina Infinium HumanMethylation450 BeadChip analysis of 21 tumor (T) and 21 non-malignant (NM) prostate specimens." (PMID 28052017, 2017).
cancer (17 papers, 2015 to 2025). A tumor composed of atypical neoplastic, often pleomorphic cells that invade other tissues. "We also observed cancer-specific promoter hypermethylation and downregulation of COL4A6, which encodes a subunit of the epithelial basement membrane protein collagen IV." (PMID 28052017, 2017). "From this list, 8 novel top candidate genes were selected based on their display of highly cancer-specific hypermethylation over multiple adjacent promoter-associated DMCs: COL4A6, CYBA, HLF, LINC0134 (LOC149234), LRRC4, PROM1, RHCG, and TCAF1 (FAM115A)." (PMID 28052017, 2017). "Furthermore, the molecular mechanisms underlying COL4A6-enhanced cancer cell invasion and chemoresistance were elucidated to provide an understanding of its mode of action." (PMID 40603853, 2025). "Notably, loss of Col4a5 and Col4a6 chains in CRC tissues have been suggested to be related to the observation that cancer cells break through the epithelial basement membrane during the early stages of cancer cell invasion." (PMID 29339782, 2018). "Among these, Col4a6 and Csf2 genes participated in inflammation-to-cancer progression by regulating the PI3K-Akt and TNF pathways." (PMID 41415031, 2025). "Based on these findings, we propose that COL4A6 increases cancer chemoresistance and may serve as a therapeutic biomarker in EOC." (PMID 40603853, 2025). "Notably, transcriptional loss of Col4a5 and Col4a6 in the epithelial basement membrane was observed in CRC and during cancer cell invasion." (PMID 29339782, 2018). "Moreover, COL4A6 promoted cancer cell sensitivity to cisplatin via DDR1/NF-κB pathway activation." (PMID 40603853, 2025). "Bioinformatics analysis identified critical candidate genes (Col4a6, Csf2) and pathways (PI3K-Akt, TNF) in inflammation-to-cancer conversion." (PMID 41415031, 2025). "The products of hub PCGs mainly function as protein binding molecule and were involved in important biological processes and signaling pathways in cancer (CDK1, MKI67, CENPF, COL4A6, DACH1, etc.)." (PMID 30026672, 2018). "The expression of COL4A6 and GADL1 may be regulated by alternative splicing-coupled NMD to promote the development of cancer." (PMID 34445498, 2021).
infection (1 paper, 2018). The state of being infected such as from the introduction of a foreign agent such as serum, vaccine, antigenic substance or organism. "In contrast, genes associated with ECM organization (Col4a5, Col4a6, Col6a4), microtubule polymerization formation (Tppp, Tppp3), and mitochondrial biogenesis (Ppargc1a) were found to be among the top down-regulated DEGs during infection." (PMID 29339782, 2018).
COL4A6 also shares sentences with these, for which no sentence is quoted: adenocarcinoma (2 papers); basal cell carcinoma (2); kidney disorder (2); ovarian cancer (2); autosomal dominant polycystic kidney disease (1); autosomal recessive Alport syndrome (1); central neurocytoma (1); Cutaneous leiomyoma (1); diabetic kidney disease (1); Down syndrome (1); follicular thyroid cancer (1); Hearing impairment (1); hereditary leiomyomatosis (1); leiomyomatosis (1); melanoma (1); mood disorder (1); myopathy (1); Nephropathy (1); neurofibroma (1); Obesity (1); ovarian failure (1); papillary renal cell carcinoma (1); renal cell carcinoma (1); steroid-resistant nephrotic syndrome (1); Stroke (1); tuberous sclerosis complex (1); Uterine leiomyoma (1); uterine leiomyosarcomas (1).